TNFSF8 (TNF superfamily member 8)
Description:
Cytokine that binds to TNFRSF8/CD30. Induces proliferation of T-cells.
Synonyms: CD153; CD30L; CD30LG; TNLG3A
Tractability: Antibody: its Gene Ontology location is reachable by antibodies, with high confidence; UniProt predicts a signal peptide or a membrane-spanning region.
Gene: Protein-coding gene on chromosome 9 (114,893,343 to 114,930,595, reverse strand). Ensembl gene ENSG00000106952.
Subcellular location: Membrane
Pathways (Reactome):
Immune System: TNFs bind their physiological receptors
Gene Ontology:
Molecular function: protein binding; signaling receptor binding; tumor necrosis factor receptor binding
Biological process: CD8-positive, alpha-beta T cell differentiation; cell-cell signaling; regulation of T cell proliferation; cell communication; immune response; signaling
Cellular component: plasma membrane; membrane
Genetic constraint (gnomAD): Loss-of-function variants: 4 observed, 17.83 expected, observed/expected ratio (o/e) 0.22, 90% interval 0.11 to 0.51. The upper end of that interval is the gene's LOEUF score, 0.51, which puts it in group 2 of 6, group 1 being the genes least tolerant of losing a copy. Missense variants: 220 observed, 269.28 expected, observed/expected ratio (o/e) 0.82, 90% interval 0.73 to 0.91. Synonymous variants: 103 observed, 108.93 expected, observed/expected ratio (o/e) 0.95, 90% interval 0.81 to 1.11.
Homologues: Orthologues: chimpanzee TNFSF8 (100% identical), macaque TNFSF8 (97% identical), dog TNFSF8 (82% identical), pig TNFSF8 (82% identical), guinea pig TNFSF8 (78% identical), rabbit TNFSF8 (78% identical), mouse Tnfsf8 (71% identical), rat Tnfsf8 (70% identical).
Diseases named in the same sentence as TNFSF8 in open-access papers:
TNFSF8 is named in the same sentence as 78 diseases in open-access papers, as found by Europe PMC text mining. Sharing a sentence is not in itself a finding about the gene and the disease. The quoted sentences say what the papers report.
lupus (11 papers, 2017 to 2025). "PBMC-derived CD4+ T cells from patients with multiple sclerosis (MS), Sjögren's syndrome (SjS), ulcerative colitis (UC), and systemic lupus erythematosus (SLE) showed lower TNFSF8 expression levels than those from the control groups." (PMID 39170389, 2024).
Hodgkins lymphoma (7 papers, 2010 to 2024). A heterogeneous group of malignant lymphoid neoplasms of B-cell origin characterized histologically by the presence of Hodgkin and Reed-Sternberg (HRS) cells in the vast majority of cases. "TNFSF8 (CD30L) is a ligand for the cell surface antigen and marker for Hodgkin lymphoma and related hematologic malignancies, TNFRSF8/CD30." (PMID 38773393, 2024).
rheumatoid arthritis (5 papers, 2011 to 2025). A chronic, systemic autoimmune disorder characterized by inflammation in the synovial membranes and articular surfaces. "Although research on TNFSF8 and TNFRSF8 is limited, existing studies suggest their elevation may be associated with chronic inflammatory diseases, including lupus erythematosus, asthma, rheumatoid arthritis, and atopic dermatitis." (PMID 40165483, 2025). "First, we utilized a publicly available scRNA-Seq data set and examined the expression of TNFSF8 and TNFRSF8 in immune cells residing in synovial tissues from joints of aged patients with rheumatoid arthritis (RA)." (PMID 34813503, 2022).
asthma (4 papers, 2013 to 2025). "TNFSF8/TNFSF15 and TNFSF13 loci are also associated with the risk of IgA nephropathy, while TNFSF4/TNFSF18 locus has previously been associated with the risk of eczema, asthma and narcolepsy, all with concordant effects to IgA levels." (PMID 36369178, 2022).
autoimmune disease (3 papers, 2020 to 2024). A disorder resulting from loss of function or tissue destruction of an organ or multiple organs, arising from humoral or cellular immune responses of the individual to their own tissue constituents. "Downregulation of TNFSF8 in T cells occurs in multiple human autoimmune diseases, indicating the existence of a common regulator of the TNFSF8-TNFRSF8 axis." (PMID 39170389, 2024). "Our results also indicated that TNFSF8-triggered signaling is involved in the pathogenesis of autoimmune diseases." (PMID 39170389, 2024). "Importantly, we found that TNFSF8 expression was decreased in the T cells of patients with AA, which can also be found in other autoimmune diseases, such as CD, SLE, and UC." (PMID 39170389, 2024). "This prompted us to further consider whether the functional information of TNFSF8 based on a mouse model is applicable to human autoimmune diseases." (PMID 39170389, 2024). "Abnormal expression of TNFSF8 has been observed in AA and other autoimmune diseases." (PMID 39170389, 2024). "Abnormal expression of TNFSF8 indicates that dysfunctional TNFSF8/TNFRSF8 signaling is involved in the pathological processes of AA, which also exists in other autoimmune diseases." (PMID 39170389, 2024). "Dysfunctional TNFSF8/TNFRSF8 signaling exists in AA and other autoimmune diseases." (PMID 39170389, 2024).
inflammatory bowel disease (3 papers, 2020 to 2024). A spectrum of small and large bowel inflammatory diseases of unknown etiology. "TNFSF8 is an important risk factor of inflammatory bowel disease (IBD) in East Asians." (PMID 39170389, 2024).
lymphoma (3 papers, 2019 to 2023). A malignant (clonal) proliferation of B- lymphocytes or T- lymphocytes which involves the lymph nodes, bone marrow and/or extranodal sites. "TNFSF8 (also known as CD153) is a cytokine that promotes cell proliferation in some lymphoma cell lines, whereas it induces cell death and suppresses cell proliferation in other lymphoma cell lines." (PMID 31511581, 2019).
mastitis (3 papers, 2020 to 2024). Inflammation of breast tissue during lactation or postpartum due to an obstructed duct or infection. "CmCGG DMEGs like IL6R, TNF, BTK, IL1R2, and TNFSF8 enriched in several immune-related GO terms and pathways indicated their important roles in host immune response and their potential as candidate genes for S. aureus mastitis." (PMID 33193625, 2020). "Moreover, genome-wide DNA methylation alteration in the format of CmCGG was significantly related to the immune response to S. aureus-induced mastitis, and several genes including IL-6R, TNF, BTK, IL-1R2, and TNFSF8 were identified as potential epigenetic markers of S. aureus mastitis." (PMID 33708235, 2020).
melanoma (3 papers, 2011 to 2025). A malignant, usually aggressive tumor composed of atypical, neoplastic melanocytes. "The 12 CpG loci identified by PAM analysis that provided the most accurate prediction of melanoma were RUNX3_P393_R, RUNX3_P247_F, RUNX3_E27_R, COL1A2_E299_F, MPO_P883_R, TNFSF8_E258_R, CD2_P68_F, EVI2A_P94_R, OSM_P188_F, ITK_P114_F, FRZB_P406_F, and ITK_E166_R." (PMID 21375697, 2011). "BCL10 (3.84-fold), TRADD (2.71-fold), CYCS (2.51-fold), DIABLO (2.43-fold), BAD (2.36-fold), BID (2.17-fold), TNFSF8 (2.13-fold), TNFSF10 (2.11-fold), BAX (2.03-fold), and FAS (2.01-fold) were also proapoptotic genes highly upregulated in response to UA treatment in A-375 melanoma cells." (PMID 39473730, 2024).
cardiac arrest (2 papers, 2023 to 2026). Cessation of breathing and/or cardiac function. "Although protein expression was relatively low in normal neurons, TNFSF8 protein expression was significantly increased and caused damage in hippocampal neurons after cardiac arrest." (PMID 36266523, 2023). "Its neuroprotective action against mitochondrial dysfunction triggered by cardiac arrest, mediated via the TNFSF8/AMPK/JNK signaling cascade, is well documented." (PMID 41523988, 2026). "Upregulating miR-483-5p inhibited the protein expression of TNFSF8, while inhibiting miR-483-5p increased the protein expression of TNFSF8 after cardiac arrest." (PMID 36266523, 2023). "In contrast, clear expression of TNFSF8 was observed on some of the hippocampal neurons of rats after cardiac arrest." (PMID 36266523, 2023). "The present study was focused on the relationship between mitochondrial dysfunction after cardiac arrest and neuroprotective effects conferred by miR-483-5p and the role that the TNFSF8/AMPK/JNK signaling pathway may play in this process." (PMID 36266523, 2023). "Furthermore, we demonstrate that TNFSF8 was the target gene of miR-483-5p and that inhibiting the expression of TNFSF8 played a neuroprotective role after cardiac arrest." (PMID 36266523, 2023).
leprosy (2 papers, 2017 to 2023). Leprosy is a chronic infectious disease affecting primarily the skin and peripheral nervous system. "For example, we have previously shown for variants of the TNFSF15/TNFSF8 genes that leprosy patients with the T1R endophenotype are largely the cause of association with the leprosy exophenotype." (PMID 28222097, 2017). "Consequently, the replication of the TNFSF15/TNFSF8 association in samples of leprosy patients with a low proportion of T1R is expected to display low power." (PMID 28222097, 2017).
lung carcinoma (2 papers, 2022 to 2025). "TNFSF8 has also been implicated in immune activation in various cancers including lung cancer and hematologic malignancies." (PMID 41228357, 2025). "A study reported that TNFSF8 expression demonstrated a negative correlation with the risk of lung cancer genesis." (PMID 36505472, 2022).
pancreatic cancer (2 papers, 2021 to 2025). "Our analyses revealed that the immune-related genes CCR4, CD19, TNFSF8, SH2D1A, ICOS, IGKV1D-39, and TNFRSF17 may be implicated in the immunophenotyping of pancreatic cancer." (PMID 34737763, 2021). "The results revealed seven immune-related genes (CCR4, CD19, TNFSF8, SH2D1A, ICOS, IGKV1D-39, and TNFRSF17) could potentially influence the immunophenotyping of pancreatic cancer." (PMID 34737763, 2021). "TNFSF8 is a member of the cytokines CD30 ligand/tumor necrosis factor superfamily and may serve as predictive biomarkers for pancreatic cancer patients' response to gemcitabine and erlotinib." (PMID 34737763, 2021).
skin carcinoma (2 papers, 2011 to 2024). "Proteins, ASIP, KRT5, CTSS, and TNFSF8, have the potential as diagnostic and therapeutic targets for skin cancers, and validation through future biological experiments is required." (PMID 39003418, 2024). "This multidimensional approach nominates ASIP, KRT5, CTSS, and TNFSF8 as potential diagnostic and therapeutic targets for skin cancers." (PMID 39003418, 2024). "ASIP was colocalized with all three types of skin cancer and STX8, KRT5, GSK3A, CTSS, and TNFSF8 with BCC." (PMID 39003418, 2024).
tuberculosis (2 papers, 2021 to 2025). A chronic, recurrent infection caused by the bacterium Mycobacterium tuberculosis. "CD153, encoded by TNFSF8, is essential for regulating CD4 + T cells in tuberculosis and may influence apoptosis control in septic ARDS." (PMID 39854144, 2025).
B-cell NHLs (1 paper, 2023). "B-cell NHLs frequently express CD27/CD27L (TNFRSF7/TNFSF7), CD30 or CD30L (TNFRSF8 or TNFSF8), CD40 (TNFRSF5), and TNFRs/TNF positive (TNFRSF1 and 2/TNFSF2), but T-cell NHLs show expression of CD30, CD40L (TNFSF5), and TNFRs/TNF." (PMID 37240076, 2023).
cervical cancer (1 paper, 2019). A primary or metastatic malignant neoplasm involving the cervix. "The interaction between TNFSF8-mediated immunity and HPV might affect the physical status of HPV DNA in patients with cervical cancer." (PMID 31511581, 2019).
Cirrhosis (1 paper, 2025). A chronic disorder of the liver in which liver tissue becomes scarred and is partially replaced by regenerative nodules and fibrotic tissue resulting in loss of liver function. "Interestingly, the expression levels of CXCL13, TNFSF8, and TNFRSF8 correlated negatively with the expression of retinol binding protein 4 (RBP4), which is decreased in cirrhosis, and positively with the expression of COL1A1, which reflects liver fibrosis." (PMID 40014629, 2025).
Crohn disease (1 paper, 2017). A gastrointestinal disorder characterized by chronic inflammation involving all layers of the intestinal wall, noncaseating granulomas affecting the intestinal wall and regional lymph nodes, and transmural fibrosis. "The TNFSF15/TNFSF8 region is a well-known locus associated with Crohn’s disease (CD) susceptibility." (PMID 28261213, 2017).
embryonal carcinoma (1 paper, 2023). A non-seminomatous malignant germ cell tumor characterized by the presence of large germ cells with abundant cytoplasm resembling epithelial cells, geographic necrosis, high mitotic activity, and pseudoglandular and pseudopapillary structures formation. "Additionally, TNFSF8 has been observed in thyroid epithelial (follicular) cells, yolk sac carcinoma, and embryonal carcinoma." (PMID 36266523, 2023).
hepatitis C virus infection (1 paper, 2025). A viral infection caused by the hepatitis C virus. "TNFSF8 gene expression plays an important role in the defence of immune cells (e.g., CD4 T cells) against Mycobacterium tuberculosis and hepatitis C virus infection." (PMID 40342962, 2025).
ischemia (1 paper, 2023). A hypoperfusion of the BLOOD through an organ or tissue caused by a PATHOLOGIC CONSTRICTION or obstruction of its BLOOD VESSELS, or an absence of BLOOD CIRCULATION. "In conclusion, the present study revealed that the miR-483-5p/TNFSF8/AMPK/JNK axis was critically involved in mitochondrial dysfunction in ischemia‒reperfusion injury in vivo and in vitro." (PMID 36266523, 2023).
malignant neoplasm of retroperitoneum (1 paper, 2024). "TNFSF8 was linked with mesothelioma, secondary malignant neoplasm of retroperitoneum and peritoneum, and mesothelioma." (PMID 39003418, 2024).
myocarditis (1 paper, 2023). Myocarditis is a condition that is characterized by inflammation of the heart muscle (myocardium). "TNFSF8 was expressed in the cardiac myocytes of mice with myocarditis, and TNFSF8 was found to be moderately or highly abundant on ventricular myocytes after treatment with IFN-γ." (PMID 36266523, 2023).
Sepsis (1 paper, 2025). Sepsis is defined as life-threatening organ dysfunction caused by a dysregulated host response to infection. "Our study identified DE‐PRGs—NDRG1, DDX3X, PTPRC, and TNFSF8—in patients with sepsis‐associated ARDS." (PMID 39854144, 2025). "This study identifies four key PANoptosis‐related genes (NDRG1, DDX3X, PTPRC, and TNFSF8) that are differentially expressed in sepsis and septic ARDS." (PMID 39854144, 2025).
Sjögren's syndrome (1 paper, 2024). "The interaction between TNFSF8 and TNFRSF8-triggered signaling in CD4+ T cells is involved in the pathogenesis of Sjögren's Syndrome." (PMID 39170389, 2024).
tumor (19 papers, 2011 to 2025). "Ultimately, AGXT2, DPYS, and TNFSF8 were selected as HCC-specific epigenetic–transcriptomic gene markers that reflect significant differences in the tumor microenvironment, exhibiting distinct cell type specificity." (PMID 41228357, 2025). "The list of genes that occur more frequently in the liver of these two strains also includes FASLG and TNFSF8, which belong to the tumour family of tumour necrosis factor." (PMID 39342330, 2024). "Of the 49 costimulatory molecules, 21 molecules (VTCN1) were upregulated and 28 molecules (TNFSF8) were downregulated in tumor tissues." (PMID 36646765, 2023). "This analysis found the expression of several potent NFκB activating cytokines in microglia, including interleukin-1β (IL-1β), TNF-α, and TNFSF8, with the corresponding receptors being expressed in tumor cells." (PMID 35803925, 2022). "We also observed increased expression levels of immune‐related genes, such as SLAMF7, TNFSF8, BTN3A1, CD2, LGALS9, PRF1, and MX2, in tumor samples from the MT group of the Local‐SCLC cohort." (PMID 38125769, 2023).
infection (9 papers, 2007 to 2025). The state of being infected such as from the introduction of a foreign agent such as serum, vaccine, antigenic substance or organism. "TNFSF8, crucial for infection and immunity, functions as an apoptosis gene, with its expression in pDMRs predicting anti‐PD‐1 immunotherapy results in small‐cell lung cancer." (PMID 39854144, 2025). "Tnfsf8 expression is mostly dispensable for control of infection outside of the lungs, and the overabundance of IFN-γ-producing CD4 T cells observed in the lungs of Tnfsf8-/- mice following infection has been shown to drive immunopathology." (PMID 35877763, 2022). "In humans, higher frequencies of M. tuberculosis specific CD153+ CD4 T cells correlate with a lower lung bacterial load, and Tnfsf8-/- mice have earlier mortality than wild-type following infection." (PMID 35877763, 2022). "In addition, Coussens and co-workers have established two genes (TNFSF8 and SELP) in a gene infection signature for Johne's disease in cattle." (PMID 17974019, 2007).
cancer (7 papers, 2011 to 2025). A tumor composed of atypical neoplastic, often pleomorphic cells that invade other tissues. "Upregulated genes included members of the tumor necrosis factor superfamily (TNFRSF9, TNFRSF11B, and TNFSF8), ABC transporters (ABCB1 and ABCG2), and nuclear factor (NF)-κB-related genes (NFKB2 and RELB), all of which induce stemness in cancer cells." (PMID 28423353, 2017).
bacterial infections (1 paper, 2025). "Additionally, we found upregulation of Tnfsf8, the ligand for CD30, which is expressed by activated CD4+ T cells and required for differentiation of both Th1 and Th17 cells during bacterial infections." (PMID 40307618, 2025).
inflammatory myopathies (1 paper, 2025). "Several tumor necrosis factor (TNF) superfamily genes (TNFSF8, LTB, TNFSF12, TNFSF13B, TNFSF14, TNFSF13, EDA) were upregulated, with LTB and EDA reaching higher levels than in other inflammatory myopathies." (PMID 41441888, 2025).
TNFSF8 also shares sentences with these, for which no sentence is quoted: Insulin resistance (8 papers); Autoimmunity (5); atopic dermatitis (4); Obesity (4); colitis (3); metabolic disorders (3); psoriasis (3); virus infection (3); anaplastic large cell lymphoma (2); glioma (2); hematologic malignancies (2); IgA nephropathy (2); Splenomegaly (2); adult T-cell leukemia/lymphoma (1); allergic asthma (1); allergic rhinitis (1); atherosclerosis (1); Behçet's disease (1); bladder tumors (1); breast carcinoma (1); Burkitt lymphoma (1); chronic kidney disease (1); chronic lymphocytic leukemia (1); colon cancer (1); eczema (1); Glucose intolerance (1); hairy cell leukemia (1); HIV-1 infection (1); kidney disease (1); latent infection (1).
A further 17 diseases each share a sentence with TNFSF8 in 1 paper.